TSSK5P (testis specific serine kinase 5, pseudogene)
Synonyms: TSSKps1; TSSK5P1; TSSK5P2
Gene: Unitary pseudogene on chromosome 8 (144,141,214 to 144,143,664, reverse strand). Ensembl gene ENSG00000227473.
Diseases named in the same sentence as TSSK5P in open-access papers:
TSSK5P is named in the same sentence as 1 disease in open-access papers, as found by Europe PMC text mining. Sharing a sentence is not in itself a finding about the gene and the disease.
TSSK5P shares sentences with these, for which no sentence is quoted: tumor (1 paper).